IL6 (interleukin 6)
Diseases named in the same sentence as IL6 in open-access papers (continued):
Sharing a sentence is not in itself a finding about the gene and the disease.
COVID-19 (continued). "Carbocysteine reduced the production of IL-6 and IL-8, decreased the expression of inflammatory cytokines such as IL-6 and TNF-α, reduced chemokines such as IL-8, IP-10 and MIP-1β (important factors related to cytokine storms of COVID-19), and exhibited exceptional anti-inflammatory ability." (PMID 36362979, 2022). "Elevated levels of FLCs in COVID-19 and healthy vaccinated against SARS-CoV-2 patients, as well as the correlation between free light chains with specific anti-SARS-CoV-2 antibodies and IL-6, reflect hyperactivation of the immune system after contact with coronavirus." (PMID 36232891, 2022). "Moreover, IL-6 expression was significantly higher in symptomatic in comparison to nonsymptomatic COVID-19 patients." (PMID 36081604, 2022). "However, serum TNF-α, IL-1β, IL-6, and blood-bacteria-free DNA were not different between healthy control and mild COVID-19 cases." (PMID 35406667, 2022). "Similarly, sarilumab – a human monoclonal antibody initially used for RA acting against IL-6 - is also under consideration for the treatment of COVID-19 if tocilizumab is not available." (PMID 36415655, 2022). "This could be explained by interleukin-6 (IL-6) which is a sensitive indicator in inflammatory conditions as it induces the synthesis of CRP during inflammation, and it was significantly higher in severe COVID-19 cases." (PMID 36064554, 2022). "If ADAM17 expression is not downregulated by SIRT1, TNF-α and IL-6 are released, resulting in an uncontrolled hyperinflammatory response as may happen with COVID-19." (PMID 35458574, 2022). "Consequently, targeting IL6, MAPK1, and MAPK3 may be a viable alternative therapeutic approach for treating CRS and COVID-19." (PMID 35992697, 2022). "Anti-IL6 antibodies (Tocilizumab), BTK inhibition with ibrutinib and acalabrutinib, as well as the known JAK inhibitors- Ruxolitinib, Fedratinib, and Baricitinib are part of potential treatment strategies against COVID-19 that combine antiviral and anti-inflammatory agents." (PMID 35663932, 2022). "A prospective cohort study of 89 patients showed that high concentrations of IL-6 followed by CRP could predict respiratory failure and the need for mechanical ventilation in patients admitted with COVID-19 with significant time difference between CRP and IL-6 in favour of IL-6." (PMID 35500008, 2022). "Regardless of the unchanged values of BDNF in different phases of COVID-19, we found a positive correlation between BDNF and MMP-9, MMP-8, and VEGF A, as well as a strong negative correlation of BDNF with IL-10 and cytokines ratios IL-10/IL-1, IL-10/IL-6, IL-10/IL-17, and IL-10/TNF-α." (PMID 36438922, 2022). "We found immune response related pathways (TGF-β, IL2-STAT5, IL6-JAK-STAT3, and TNFα signaling, Complement system activation, and Inflammatory response pathway) to be upregulated in the classical monocyte, NK cells, activated CD4+ T cells and CD4+ central memory T cells in active COVID-19 patients." (PMID 36532041, 2022). "Therefore, inhibition of neddylation might play a role in modulation Il-6 and MCP-1, which have a significant impact on the immune response of COVID-19 patients." (PMID 35831294, 2022). "In the present study, we measured the levels of NP, CRP, and IL-6 in patients suffering from COVID-19 and those with noninfectious respiratory symptoms and compared their correlations to examine whether these values would reflect similar biological processes." (PMID 35529699, 2022). "Given the importance of IL-6 in the pathophysiology of COVID-19-related ARDS, this could have a negative impact on patient outcome." (PMID 35860245, 2022). "Another study of COVID-19 patients found a negative correlation between the serum concentration of IL-6 and the level of HLA-DR expression on the CD14+ monocytes, as well as between the total number of lymphocytes and the absolute number of HLA-DR mRNA isolated from CD14+ monocytes." (PMID 35632823, 2022).
COVID-19 (continued). "They concluded that COVID-19-induced organ impairment is mostly facilitated by cytokine storms and that strategies to diminish or eradicate inflammatory cytokines would be effective in avoiding cytokine-induced organ injury, aiming to reduce IL1, IL6, TNF-α, and INF-γ levels." (PMID 35891270, 2022). "Interestingly, the total amount of triglycerides (TPTG) only showed negative correlations with cytokines, despite both TPTG and IL-6, for example, rising strongly in COVID-19." (PMID 36557315, 2022). "The immunopathology of COVID-19 allows for the monitoring of patient status, for example, via increases in the hepatic C-reactive protein (CRP), ferritin, D-dimer, and cytokines such as interleukin-6 (IL-6), or via the depletion of lymphocytes and specifically CD4+T cells." (PMID 35888742, 2022). "Moreover, ROC analysis revealed that IL-6, TXA2, and NF-κB p65 could be useful in predicting the possibility of infection with COVID-19, and IL-6 could be of possible significance as a good predictor of the severity and disease progress." (PMID 36298501, 2022). "This hypothesis is consistent with studies demonstrating defects in dendritic cell response during COVID-19, and other data demonstrating a strong negative correlation between plasma IL-6 levels and monocytes HLA-DR expression." (PMID 35421120, 2022). "Notably, the cytokines that we investigated are normally expressed in human tissue; in particular, as shown by our data, IL-1β, IL-6, and IFN-β are constitutively basally expressed in control cases, while IFN-λ is more expressed in control lung tissue and downregulated in COVID-19 patients’ lungs." (PMID 36422642, 2022). "CSF IL-6 and IL-8 were also still elevated in the repeat sample with the longest follow-up tested, which was obtained 16 days after neurological and 35 days after non-neurological COVID-19 onset." (PMID 35057809, 2022). "We provide new information on the incompletely understood role of IL-6 signalling in COVID-19 patients, which might be useful not only as biomarkers of severity but also in designing new treatment strategies." (PMID 35634332, 2022). "Importantly, another study has shown that BBR (900 mg/day, for 14 days) also could significantly reverse the changes in IL-6, TNF-α and C-reactive protein (CRP) levels in patients with severe COVID-19 with diarrhoea." (PMID 36147356, 2022). "Indeed, an increase in cytokines such as TNF-α, MCP-1, IL-6, IL-1β, and IL-10 was shown in the rat ARDS model induced by LPS administration, which corresponds to the cytokine profile of patients with a severe form of COVID-19." (PMID 36290634, 2022). "However, further investigation is needed to evaluate if both markers may be used in conjunction with other predictive markers for COVID-19 such as C-reactive protein (CRP), IL-6, procalcitonin (PCT), D-dimer and serum ferritin." (PMID 36615083, 2022). "Although IL-6 is elevated in the serum of patients with severe COVID-19, there was no significant inflammatory cytokine/chemokine induction by SARS-CoV-2 in our in vitro models, whereas in separate experiments increased cytokine levels were induced in cells exposed to rhinovirus or Poly I:C." (PMID 35359837, 2022). "In a retrospective study of COVID-19 patients treated with netakimab, the IL-6 antagonist tocilizumab, or no treatment, the netakimab treated group showed significantly less mortality, ICU admission, and mechanical ventilation requirement than the other two groups." (PMID 35572514, 2022). "The second phase, which is much more crucial in COVID-19 because it is an intracellular viral infection, results in the secretion of a variety of cytokines into the bloodstream by T cells and macrophages, of which IL1-β, IL-2, IL-8, IL-10, IL-6, IL-12, IFN-γ, and TNF-α are the best known." (PMID 35874678, 2022).
COVID-19 (continued). "In patients infected with SARS-CoV-2, higher levels of the proinflammatory cytokines IL-1β, IL-6, IL-8, IL-13, IL-17, RANTES, and IFN-γ were found, and these increased cytokines and chemokines mediated the infection immunopathogenesis and played important roles in the progression of COVID-19." (PMID 35893674, 2022). "In addition, we found that non-critical hospitalized COVID-19 patients with low FT3 show higher IL-6 levels and a specific metabolomic profile with higher ketogenesis." (PMID 36440226, 2022). "In addition, IL-6 and PAI-1 form a vicious cycle of inflammation and thrombosis, which may contribute to the poor prognosis of patients with severe COVID-19." (PMID 35784318, 2022). "However, there are several limitations, this model does not account for treatments validated in the management of COVID-19 such as immunomodulators or interleukin-6 inhibitors, due to limitations in the methods of data collection employed at some sites." (PMID 36031619, 2022). "The retrospective analysis included serum cytokines (interleukins; IL-1β, IL-6, IL-8 and tumour necrosis factor (TNFα)) measured using EllaTM (Bio-Techne, Oxford, UK) and PCT measured by Roche Cobas (Burgess Hill, UK) in patients admitted with COVID-19 between March 2020 and January 2021." (PMID 35500008, 2022). "Therefore, it is likely that ORF3a-induced IL-6 and TNF-α production through NF-κB, TLR3 or TLR4 could all contribute to the severity of COVID-19." (PMID 35356515, 2022). "More generally, we had no data regarding treatments, so the impact of other drugs that could influence the severity of COVID-19 in hospitalized patients (e.g., dexamethasone, IL6 inhibitors, or ARA2 inhibitors) was also not assessed." (PMID 33801131, 2021). "Similarly, the lower respiratory microbiome, including the lung microbiome, shows decreased diversity in ARDS patients without COVID-19, with increased abundance of Staphylococcus, Streptococcus, and Enterobacterales species and increased IL-6 levels." (PMID 34161373, 2021). "However, some trials have reported a lack of improvement in COVID-19 patient mortality upon IL-6 inhibitor treatment." (PMID 34768321, 2021). "Furthermore, we found that the kinetic changes of ferritin levels, but not those of D-dimer and IL-6, correlate with COVID-19 progression." (PMID 33596963, 2021). "Decreasing insulin resistance, reduction of some inflammatory cytokines like IL-6 and TNF-α, modulation of angiotensin-converting enzyme 2 (ACE2) receptor, and improving neutrophil to lymphocyte ratio are some of the potential mechanisms of metformin in COVID-19 patients with DM." (PMID 33815295, 2021). "The top five targets identified based on candidate gene prioritization were C3, CFB, EGFR, IL6, and TLR2, where the 39 common core genes were used as a test set, and 1899 genes from the COVID-19 pathway (KEGG) and our multi-omics datasets were used as training sets." (PMID 34067609, 2021). "However, severe COVID-19 patients exhibit sustained systemic hyper-inflammation state and cytokine storms, characterized by lymphopenia and the elevation of TNF-alpha, IL-1, and IL-6." (PMID 34344306, 2021). "Amongst the remaining COVID-19 patients, greatly elevated levels of inflammatory cytokines/chemokines were detected in respiratory samples, with concentrations being 60× (MCP-1), 400× (IL-6) and 780× (IL-8) higher than in plasma for DRASTIC-032, −037, −056, −063." (PMID 34462740, 2021). "Additionally, ferritin and C-reactive protein appear to be screening tools for the early diagnosis of a systemic inflammatory response syndrome in patients with a severe form of COVID-19 (denominated CSS), with lower cost and wider availability in frontline clinical practice than IL-6." (PMID 34185801, 2021).
COVID-19 (continued). "Another study of 12 patients with neurological complications presenting with post-COVID-19 symptoms between 9 and 12 weeks post-onset found an acute inflammatory phase with significantly elevated inflammatory parameters including C-reactive protein CRP and IL-6 levels." (PMID 34685427, 2021). "In addition, increased levels of proinflammatory cytokines (Interleukin-1, Interleukin-6, and TNF) were found in COVID-19 patients, which may explain the endothelial dysfunction to some degree." (PMID 34945800, 2021). "In the early phases of COVID-19, the proinflammatory response often predominates, with the massive production of proinflammatory cytokines such as tumor necrosis factor (TNF)-a, IL-8 and IL-6 that stimulate the effector functions of neutrophils, macrophages and Th1 cells." (PMID 34441796, 2021). "Moreover, the COVID-19-induced inflammation and cytokine storm (CS), which are characterized by profound elevations in the levels of tumor necrosis factor-alpha (TNF-α) and interleukin (IL)-6, lead to peripheral insulin resistance (IR)." (PMID 34124187, 2021). "Interestingly, LMWH seems exert anti-inflammatory effects by reducing IL-6 and increasing lymphocyte %, so that the potential of LMWH could be to mitigate cytokine storm in severe COVID-19 patients." (PMID 33544720, 2021). "Moreover, in comparison to wave 1, only IP-10 levels were significantly higher in severe versus mild COVID-19 patients, with no change of IL-1ra and IL-6 levels." (PMID 34675240, 2021). "Furthermore, an uncontrolled, exploratory study showed that for patients with COVID-19, IFN-α2b therapy appeared to shorten the duration of viral shedding, accelerating viral clearance from the respiratory tract and reducing the concentration of IL-6." (PMID 33467912, 2021). "Elevated IL-6 and nonspecific symptoms were observed in patients with COVID-19." (PMID 37287491, 2021). "The levels of IL-8, IL6, and CRP were elevated above the normal range in both survived and deceased patients; however, all three inflammatory markers were approximately 2-4-fold higher in deceased COVID-19 patients compared to patients who recovered (p<0.0001)." (PMID 34228746, 2021). "The sera IL-6 levels in COVID-19 patients correlated positively with the percentage of Mo-MDSC and somewhat lesser with PMN-MDSC, but negatively with the percentage of monocytes, suggesting that Mo-MDSC mostly contribute to serum IL-6 in severe COVID-19 patients." (PMID 33692788, 2021). "Tocilizumab was approved for treatment in patients with serious COVID-19 presenting elevated IL-6 levels by the Chinese National Medical Products Administration (NMPA) in March 2020, and this treatment has been proposed as a candidate therapy for severe COVID-19." (PMID 33404925, 2021). "These IL-6-related signaling targets, including sIL-6R and the JAK-STAT signaling pathway, may represent new approaches to limit hyperinflammation and cytokine storms in patients with COVID-19." (PMID 33404925, 2021). "A significant increasing trend of IL-1β, IL-1ra, IL-2, IL-4, IL-5, IL-6, IL-7, IL-8, IL-10, IL-12(p70), IL-15, IL-17, FGF-b, G-CSF, GM-CSF, IFN-γ, IP-10, MCP-1, MIP-1α, PDGF, TNF-α, and VEGF was observed in the three groups (Controls ≤ Mild COVID-19 ≤ Severe COVID-19)." (PMID 34675240, 2021). "However, transcriptional modules to quantify IL-1β or IL-6 response have not been used in COVID-19 to quantify the bioactivity of these cytokine pathways in vivo." (PMID 33319166, 2021). "The dexamethasone therapy itself may not influence IL-6 level, which is supported by an analysis of the transcriptomic data that indicates the therapeutic mechanism of dexamethasone in severe COVID-19 patients does not involve IL-6 pathway." (PMID 34441262, 2021).
COVID-19 (continued). "From the results of COVID-19 clinical research, we can find CPMs can regulate the proportion of lymphocyte and leukocyte, significantly reduce the level of inflammation factors such as CRP, D-dimer, PCT, IL6, IL10, IL17, TNF-α, and IFN-γ, and increase the level of IL4." (PMID 34335247, 2021). "Although no clear correlation has been found between COVID-19 patients with GI symptoms and IL-6 levels, IL-6 may become a potential target for immunotherapy for COVID-19 pneumonia." (PMID 34222268, 2021). "Indeed, COVID-19 patients that used metformin showed lower IL-6 levels compared to non-metformin users at admission." (PMID 34256824, 2021). "Finally, IFNα and IL6 served only as early immune responses directed against SARS-CoV-2 but not the severity of the disease in both active and convalescent COVID-19 phases." (PMID 34867943, 2021). "Common inflammatory markers seen in endothelial dysfunction including C-reactive protein (CRP), IL-6, interferon gamma-induced protein-10 (IP-10), monocyte chemoattractant protein-1 (MCP-1), macrophage inflammatory protein-1 alpha (M1P1A), and TNF-α were also elevated in patients with COVID-19." (PMID 34012410, 2021). "Particularly, the CRS-related cytokines, including IL-6, IL-1β, IL-10, IL-18, and IFN-γ, displayed progressive increase along disease severity from healthy controls to mild and severe patients, highlighting the broad and strong inflammatory responses in severe COVID-19 patients." (PMID 33712622, 2021). "Whereas serum of non-COVID-19 patients and anti-spike IgG-negative COVID-19 patients showed no up-regulation of pro-inflammatory cytokines compared to individual poly(I:C) stimulation, IL-1β, IL-6, IL-8, and TNF production was amplified by serum of COVID-19 patients with anti-spike IgG (P <0.0001)." (PMID 33979301, 2021). "In this regard, a clinical trial performed on COVID-19 patients indicated the ability of a nanomicellar form of CUR to significantly decrease the mRNA expression and cytokine secretion levels of IL-6 and IL-1β, which may ameliorate disease's clinical manifestation and promote overall recovery." (PMID 34584616, 2021). "In a recent study of 655 COVID-19 patients presented to the Emergency Department at a University Hospital of which 15% were hospitalized, 42% of hospitalized patients had elevated AST levels and higher serum CRP, lactate dehydrogenase (LDH), ferritin and IL-6 levels." (PMID 34287285, 2021). "IL-6 was shown to down-regulate MHC II expression and IL-12 production by DC, which might explain the findings on impaired induction of type 1 response in T cells and diminished HLA-DR expression in COVID-19." (PMID 33692788, 2021). "Given the vital role of cytokine storm in the pathogenesis of COVID-19, agents able to reduce the release of many cytokines involved in the initiation and progression of inflammation (such as IFN-γ, IL-6, and TNF-α) may assist in preventing the progression of the disease." (PMID 33995078, 2021). "Whilst the levels of some cytokines (i.e., IL-6, IL-8, IP-10, TNF-α, sCD25) declined one month after the SARS-CoV-2 diagnosis, others (MIP-1β, IL-1β, MIP-1α and IFN-γ) showed higher levels at month 1 and/or 3 in patients with mild/moderate disease compared to those with severe COVID-19." (PMID 34835384, 2021). "Furthermore, NF-κB, IL-6, and TNF are considered promising therapeutic targets in COVID-19." (PMID 34580601, 2021). "In a large multicentre, retrospective, cohort study involving 232 cancer patients and 519 patients without cancer, increased TNF-α and IL-6, as well as decreased lymphocytes and CD4+ T cells, were found to be risk factors for disease aggravation in patients with cancer and COVID-19." (PMID 34123873, 2021).